CD40LG (CD40 ligand)
Description:
Cytokine that acts as a ligand to CD40/TNFRSF5. Costimulates T-cell proliferation and cytokine production. Its cross-linking on T-cells generates a costimulatory signal which enhances the production of IL4 and IL10 in conjunction with the TCR/CD3 ligation and CD28 costimulation. Induces the activation of NF-kappa-B. Induces the activation of kinases MAPK8 and PAK2 in T-cells. Induces tyrosine phosphorylation of isoform 3 of CD28. Mediates B-cell proliferation in the absence of co-stimulus as well as IgE production in the presence of IL4 (By similarity). Involved in immunoglobulin class switching (By similarity). [CD40 ligand, soluble form]: Acts as a ligand for integrins, specifically ITGA5:ITGB1 and ITGAV:ITGB3; both integrins and the CD40 receptor are required for activation of CD40-CD40LG signaling, which have cell-type dependent effects, such as B-cell activation, NF-kappa-B signaling and anti-apoptotic signaling.
Synonyms: CD40-L; TRAP; CD154; CD40L; TNFSF5; gp39; hCD40L; HIGM1; T-BAM; IGM; IMD3
Tractability: Small molecule: a structure with a bound ligand is known; it has a high-quality binding pocket. Antibody: a drug acting on it is in phase 2 or 3 trials; UniProt places it where antibodies can reach, with high confidence; its Gene Ontology location is reachable by antibodies, with high confidence; UniProt predicts a signal peptide or a membrane-spanning region. PROTAC: a small molecule that binds it is known. Other modalities: a drug acting on it is in phase 2 or 3 trials.
Target class: Secreted protein
Gene: Protein-coding gene on chromosome X (136,648,158 to 136,660,390, forward strand). Ensembl gene ENSG00000102245.
Subcellular location: Cell membrane; Cell surface; Secreted (CD40 ligand, soluble form)
Subcellular location (Human Protein Atlas): Golgi apparatus; Plasma membrane; Predicted to be secreted
Pathways (Reactome):
Immune System: Immunoregulatory interactions between a Lymphoid and a non-Lymphoid cell; TNF receptor superfamily (TNFSF) members mediating non-canonical NF-kB pathway; TNFR2 non-canonical NF-kB pathway
Gene Ontology:
Molecular function: CD40 receptor binding; cytokine activity; integrin binding; protein binding; protein serine/threonine kinase activator activity; signaling receptor binding; tumor necrosis factor receptor binding
Biological process: B cell proliferation; CD40 signaling pathway; inflammatory response; integrin-mediated signaling pathway; negative regulation of apoptotic process; platelet activation; positive regulation of endothelial cell apoptotic process; positive regulation of interleukin-10 production; positive regulation of interleukin-12 production; positive regulation of interleukin-4 production; positive regulation of T cell proliferation; cell surface receptor signaling pathway; isotype switching; leukocyte cell-cell adhesion; positive regulation of canonical NF-kappaB signal transduction; positive regulation of extrinsic apoptotic signaling pathway; T cell costimulation; cell communication; immune response; regulation of gene expression; regulation of immune system process; signaling
Cellular component: cell surface; extracellular region; plasma membrane; membrane; external side of plasma membrane
Gene-disease validity (ClinGen):
ClinGen rates the evidence that CD40LG causes each of these diseases.
hyper-IgM syndrome type 1 (X-linked): Definitive. The X-linked variant of the Hyper-IgM syndrome.
Homologues: Orthologues: chimpanzee CD40LG (99% identical), macaque CD40LG (98% identical), pig CD40LG (86% identical), rabbit CD40LG (86% identical), guinea pig CD40LG (84% identical), dog CD40LG (83% identical), rat Cd40lg (78% identical), mouse Cd40lg (77% identical), tropical clawed frog cd40lg (38% identical). Paralogues in human: TNFSF10 (21% identical), TNFSF15 (20% identical), TNFSF11 (18% identical), FASLG (18% identical), TNFSF14 (18% identical), TNF (17% identical), LTB (16% identical), LTA (13% identical).
Diseases named in the same sentence as CD40LG in open-access papers:
CD40LG is named in the same sentence as 1,296 diseases in open-access papers, as found by Europe PMC text mining. Sharing a sentence is not in itself a finding about the gene and the disease. The quoted sentences say what the papers report.
COVID-19 (1,485 papers, 2020 to 2026). A disease caused by infection with severe acute respiratory syndrome coronavirus 2. "In addition, elevated plasma levels of soluble CD40 ligand (sCD40L) have been observed in moderate to severe COVID-19, associated with a platelet-driven prothrombotic profile." (PMID 41346576, 2025). "Enhanced release of P-selectin, CD40 ligand, PAI-1, and CCL5 mediated via GPVI was linked to a higher risk of requiring invasive or non-invasive ventilation and/or mortality in COVID-19 patients." (PMID 41012635, 2025). "Imatinib, a protein kinase inhibitor predicted for target CD40LG gene, has been reported to ameliorate COVID-19-induced metabolic complications." (PMID 36923793, 2023). "For further analysis, NKT cells of 202 COVID-19 patients and 28 controls were grouped into 6 cell subtypes, including NKT_CD4_CD40LG, NKT_CD4_TIM3_CD62L, NKT_CD8, NKT_CD8_CD40LG, NKT_CD8_TIM3, and NKT_DN_ITGAX." (PMID 35250975, 2022). "The gradual decrease in the expression of CD40 and CD40LG in the COVID-19 positive and recovered groups suggest an enhanced infection-induced inflammation and apoptosis of CD8+ T cells during COVID-19 infection." (PMID 36532041, 2022). "CD40 ligand and galectin-9 were both distinctly increased in patients with COVID-19 (i.e. P<0·0001 for COVID-19 versus CAP-other)." (PMID 35660785, 2022). "The transmembrane glycoprotein CD40 ligand and the cytotoxic molecule granzyme B showed a significant increase in mild-moderate COVID-19 patients compared to healthy controls." (PMID 35529862, 2022). "PD-L1 was higher in severe COVID-19 patients, whereas the levels of CD40 ligand and granzyme B showed a significant increase in mild-moderate COVID-19 patients, but reduced in severe patients." (PMID 35529862, 2022). "Together, the results indicate a CD40-CD40 ligand interaction mediated increase of the cytokine response and abnormal T cell activation in the COVID-19 positive individuals." (PMID 36532041, 2022). "In the lungs, COVID-19 causes lung dysfunction by regulating the expression of SRC, RHOA, CD40LG, CSF1, and TNFRSF1A." (PMID 34504502, 2021). "To interrogate the potential role of T cell activation–related biomarkers in COVID-19 immunopathogenesis, we measured levels of IL-2, sCD25 (or sIL-2Rα), soluble CD40 ligand (sCD40LG), soluble FAS ligand (sFASLG), IL-7, and IL-3." (PMID 33232303, 2021). "Gene expression analyses of COVID-19 autopsy tissue also demonstrated downregulation of CD40LG, which is an essential link of communication between T and B cells and significantly influences B cell maturation." (PMID 33950285, 2021). "Th1 more than Th2 immune response–associated biomarkers are increased in patients with COVID-19, while soluble FAS ligand and soluble CD40 ligand are decreased." (PMID 33232303, 2021). "Lastly, CD40 ligand (CD40L) was significantly higher in moderate and severe COVID-19 patients." (PMID 38855114, 2024). "COVID-19 ARDS patients had significantly higher plasma concentrations of CCL5 (p = 0.025) and non-significantly higher plasma concentrations of CXCL2 (p = 0.094), CXCL10 (p = 0.287), CD40 ligand (p = 0.125), IL-10 (p = 0.232), and GM-CSF (p = 0.332) compared with non-COVID-19 ARDS patients." (PMID 33138839, 2020). "Hence, our findings offer new insights into the molecular mechanisms underlying COVID-19 and sepsis-induced ARDS and suggest CD3, CD247, CD2, CD40LG MMP-9, LCN2, and RETN as the potential targets for neutrophils in developing novel therapies and diagnostic tools for these diseases." (PMID 37822934, 2023). "Gene expression regulation of ACE2 and other X-chromosome linked genes, including Toll-like receptors (TLRs), CD40 ligand (CD40L), and Forkhead box P3 (FOXP3)/Scurfin, expressed upon SARS-CoV-2 infection, may play a critical role in COVID-19 pathogenesis and severity." (PMID 34691068, 2021).
COVID-19 (continued). "We aimed to evaluate the role of NETs (citrullinated histone H3 [CitH3], cell-free DNA [cfDNA]) and platelet activation markers (soluble CD40 ligand [CD40L] and P-selectin) in estimating the hazard of different clinical trajectories in patients with COVID-19." (PMID 37047662, 2023). "Of these, six hub genes (CD247, CD2, CD40LG, KLRB1, LCN2, RETN) showed significant alterations across COVID-19, sepsis, and geriatric sepsis-induced ARDS." (PMID 37822934, 2023). "The immune and inflammatory response in the COVID-19 patients, as revealed by the cell-cell communication analysis, is modulated not only by CD22-CD45 interaction, but also CD40 and CD40LG interaction." (PMID 36532041, 2022). "Eight genes associated with platelet activation and pro-thrombosis were upregulated in COVID-19 patients: MPIG6B, HBB, HPSE, CD40LG, STXBP3, CLEC1B, TFPI and GNAS." (PMID 35477940, 2022). "Our data add to the findings on various markers of endothelial cell and platelet activation, including vWf, soluble thrombomodulin, soluble CD40 ligand, and plasminogen activator inhibitor (PAI)-1, studied in COVID-19." (PMID 33477776, 2021). "A single-center cross-sectional study showed that the platelet activation marker soluble CD40 ligand (sCD40L) was significantly higher in intensive care unit (ICU) patients than in non-COVID-19 and non-hospitalized controls." (PMID 36248790, 2022). "Besides, we identified a CD40-CD40 ligand interaction-mediated increased inflammatory, immune and stress response by the monocyte, NK cells, CD4+ TCM, and CD8+ T cell populations in the COVID-19 patients." (PMID 36532041, 2022). "CD247, CD2, CD40LG, and KLRB1 displayed a positive correlation with CD8+ T cells and CD4+ T cells in both COVID-19 and sepsis cases, while LCN2 and RETN showed a negative correlation." (PMID 37822934, 2023). "We show that plasma CXCL2, CXCL10, CCL5, CD40 ligand, IL-10, and GM-CSF concentrations and ELF CXCL1, CXCL10, granzyme B, TRAIL, and EGF concentrations were found in greater concentrations in COVID-19 than in non-COVID-19 ARDS patients." (PMID 33138839, 2020). "Additionally, platelets from patients with community-acquired pneumonia, with or without COVID-19, release chemokines, PAI-1, and CD40 ligand." (PMID 41012635, 2025).
viral infection (394 papers, 2004 to 2026). "Increased CD40LG expression is strongly linked with severe viral infection with higher CD40LG observed in intensive care patients and detectable in plasma samples." (PMID 40981223, 2025). "Finally, our program supports the role of hsa-miR-122-5p during viral infection via regulation of CD40LG." (PMID 40981223, 2025). "Established cultures of infected cells maintained this phenotype, while parallel mock-infected cultures switched immunoglobulin heavy chain isotype usage, a likely consequence of continuous CD40 ligand and IL-4 stimulation, suggesting that virus infection suppresses isotype switching." (PMID 26819313, 2016). "After this screening, four genes (STAG2, CD40LG, SMARCA2 and OLFML3) were found to have predictively high scores from the databases and their established links to the immune response and viral infection." (PMID 40981223, 2025). "Similarly, CD40-Ligand (CD40L) is expressed on activated platelets, and can trigger an inflammatory response by interacting with CDBoth P-selectin and CD40L can be measured with a bead-based multiplex immunoassay and were associated with worse outcomes both in bacterial and viral infections." (PMID 35159235, 2022). "For other viral infections such as Respiratory Syncytial Virus (RSV), the fusion of a viral protein with CD40 ligand delivered by an adenoviral vector into BALB/c mice effectively protected animals against the viral infection, inducing neutralizing antibodies and memory CD8+ T-cells." (PMID 36016929, 2022).
lupus (375 papers, 2003 to 2026). "Lastly, the X-linked gene TNFSF5, encoding the CD40 ligand, which is important in T cell-dependent B-cell stimulation, is also hypomethylated and over-expressed in T cells of lupus patients." (PMID 28085900, 2017). "A number of other X chromosomal genes, including that encoding CD40 ligand, have been found to be overexpressed in T cells of women with lupus as a consequence of gene demethylation on an otherwise inactivated X chromosome." (PMID 24711544, 2014). "Higher levels of CD40LG may be associated with thrombogenesis, inflammation, atherosclerosis, coronary artery syndrome, and systemic lupus erythematosus." (PMID 39769502, 2024). "In addition, the hypomethylation and overexpression of X chromosome-linked genes such as CD40LG and miRNAs have been implicated in the female dominance of lupus." (PMID 34062726, 2021). "The implications of the CD40-CD40 ligand (CD40L) signaling pathway in systemic lupus erythematosus (SLE) were well documented, due to its important role among immune cells." (PMID 35001849, 2022). "Smaller PEVs in lupus were determined to have decreased mitochondrial proteins but increased glycolytic and apoptotic proteins, including annexin V, CD40 ligand, and galectin-3 binding protein G3BP." (PMID 35887184, 2022). "CD40 ligand (CD40L) blockade showed promise in initial clinical trials of lupus, although therapeutic development was halted because of thrombotic side effects." (PMID 31440232, 2019). "Blockade of CD40 ligand (CD40L) showed promising effects in early lupus clinical trials, even though development was halted due to thrombotic side-effects." (PMID 29330524, 2018). "An increase of soluble CD40LG (sCD40LG) has been observed in many autoimmune diseases, such as systemic lupus erythematosus (SLE), rheumatoid arthritis (RA), and Graves disease (GD)." (PMID 22731751, 2012). "Aberrant CD40 ligand (CD154) expression occurs on both T cells and B cells in human lupus patients, which is suggested to enhance B cell CD40 signaling and play a role in disease pathogenesis." (PMID 21799861, 2011). "Such increased expression of several X chromosome-linked genes has been proposed in lupus, allowing certain immune-related genes such as TLR-7, TASL, CD40 ligand (CD40L), and Bruton’s Tyrosine Kinase (BTK) to be expressed from both X chromosomes in female cells." (PMID 41283475, 2025). "Activated CD40 ligand (sCD40L) is upregulated in patients with lupus." (PMID 33008090, 2020). "Reduced expression of DNA (cytosine-5)-methyltransferase (DNMT)s and global DNA hypomethylation are observed in both human and murine lupus CD4+ T cells, which are associated with increased expression of autoimmune associated genes such as CD40 ligand (CD40L) and TNFSF7 (CD70) in lupus T cells." (PMID 27070142, 2016). "The increase in CD40 may instead participate in disease pathogenesis, being present months before any sign of autoimmunity, and its downregulation should be explored as an alternative to treatment with anti-CD40 ligand in lupus." (PMID 16507174, 2006). "promoter and enhancer demethylation may cause CD40LG overexpression on CD4+ T cells in women but not men with lupus." (PMID 38510251, 2024). "Current evidence shows that the CD40–CD40 ligand (CD40–CD40L) system plays a crucial role in the development, progression and outcome of systemic lupus erythematosus (SLE)." (PMID 26474561, 2015). "Meanwhile, decrease in methylation level of several immune-related genes, e.g. TGAL (integrin alpha L chain, CD11a), CD40LG, TNFSF7 (CD70), KIR2DL4, and PRF1, can influence their expression in lupus T-cells." (PMID 29803202, 2018). "Subsequently, hypomethylation of certain genes have been identified as important in lupus T cells, such as ITGAL (CD11a), CD40LG (CD40L), TNFSF7 (CD70), Killer-cell immunoglobulin-like receptor (KIR2DL4), perforin (PRF1), and CD5 in lupus B cells." (PMID 25566322, 2014). "Activated B cells express CD40 ligand CD154 in both patients with SLE and lupus prone mice." (PMID 25296026, 2014).
lupus (continued). "The genes encoding perforin (PRF1), CD11a (ITGAL), CD70 (TNFSF7), CD40L (CD40LG), and the killer cell immunoglobulin-like receptor (KIR) genes are normally suppressed by DNA methylation in CD4+ T cells, but are demethylated and over-expressed by CD4+ T cells from patients with active lupus." (PMID 28239687, 2016).
malaria (300 papers, 2005 to 2026). Malaria is a serious and sometimes fatal disease caused by a parasite that commonly infects a certain type of mosquito which feeds on humans. "Some genetic variations, such as those found in the hemoglobin subunit beta (HBB), ABO blood group (ABO), ATPase plasma membrane Ca2+ transporting 4 (ATP2B4), glucose-6-phosphate dehydrogenase (G6PD) and CD40 ligand (CD40LG) loci, have been associated with attenuation of severe malaria." (PMID 36895563, 2023). "The CD40LG gene maps to chromosome X and hemizygous males or homozygous females for the minor allele at rs3092945 in the promoter region showed increased resistance to severe malaria an effect that was detected in a multicentric study but was subjected to modifiers in different populations." (PMID 31417551, 2019). "We revisited genetic evidence provided by inflammatory response genes that have been repeatedly associated to malaria, namely TNF, NOS2, IFNAR1, HMOX1, TLRs, CD36, and CD40LG." (PMID 31417551, 2019). "The absence of an association between CD40LG and a specific phenotype of severe malaria in our current study presumably reflects the greater power of our study relative to earlier studies, because small studies are prone to false-positive findings as a result of statistical chance." (PMID 30033078, 2018).